SELENOK (selenoprotein K)
Description:
Required for Ca(2+) flux in immune cells and plays a role in T-cell proliferation and in T-cell and neutrophil migration (By similarity). Involved in endoplasmic reticulum-associated degradation (ERAD) of soluble glycosylated proteins. Required for palmitoylation and cell surface expression of CD36 and involved in macrophage uptake of low-density lipoprotein and in foam cell formation (By similarity). Together with ZDHHC6, required for palmitoylation of ITPR1 in immune cells, leading to regulate ITPR1 stability and function. Plays a role in protection of cells from ER stress-induced apoptosis. Protects cells from oxidative stress when overexpressed in cardiomyocytes.
Synonyms: SelK; HSPC030; HSPC297
Tractability: Antibody: UniProt places it where antibodies can reach, with high confidence; UniProt predicts a signal peptide or a membrane-spanning region; its Gene Ontology location is reachable by antibodies, with medium confidence. PROTAC: UniProt records ubiquitination sites on it.
Gene: Protein-coding gene on chromosome 3 (53,884,417 to 53,891,885, reverse strand). Ensembl gene ENSG00000113811.
Subcellular location: Endoplasmic reticulum membrane; Cell membrane
Subcellular location (Human Protein Atlas): Cytosol; Nucleoplasm
Gene Ontology:
Molecular function: identical protein binding; protein binding
Biological process: intrinsic apoptotic signaling pathway in response to endoplasmic reticulum stress; protein palmitoylation; response to oxidative stress; calcium ion transport; endoplasmic reticulum calcium ion homeostasis; positive regulation of chemokine production; positive regulation of defense response to virus by host; positive regulation of interleukin-6 production; positive regulation of monocyte chemotactic protein-1 production; positive regulation of tumor necrosis factor production; regulation of calcium-mediated signaling
Cellular component: endoplasmic reticulum; endoplasmic reticulum membrane; plasma membrane; Golgi apparatus
Genetic constraint (gnomAD): Loss-of-function variants: 1 observed, 3.41 expected, observed/expected ratio (o/e) 0.29, 90% interval 0.1 to 1.34. That is too few expected variants to judge how well the gene tolerates losing a copy. Missense variants: 51 observed, 33.93 expected, observed/expected ratio (o/e) 1.5, 90% interval 1.2 to 1.86. Synonymous variants: 19 observed, 10.11 expected, observed/expected ratio (o/e) 1.88, 90% interval 1.22 to 1.97.
Homologues: Orthologues: chimpanzee SELENOK (99% identical), dog SELENOK (98% identical), macaque SELENOK (97% identical), pig SELENOK (95% identical), rabbit SELENOK (95% identical), rat Selenok (93% identical), mouse Selenok (91% identical), zebrafish selenok (65% identical), tropical clawed frog selenok (61% identical), Caenorhabditis elegans Y41E3.8 (35% identical).
Diseases named in the same sentence as SELENOK in open-access papers:
SELENOK is named in the same sentence as 27 diseases in open-access papers, as found by Europe PMC text mining. Sharing a sentence is not in itself a finding about the gene and the disease. The quoted sentences say what the papers report.
melanoma (7 papers, 2018 to 2025). A malignant, usually aggressive tumor composed of atypical, neoplastic melanocytes. "SELENOK is associated with the prognosis of lung adenocarcinoma and melanoma and can be a potential target for tumour immunotherapy." (PMID 35883755, 2022). "Overall, SELENOK deficiency in melanoma cells led to reduced capacity for IP3R-generated Ca2+ flux and altered gene transcription in a manner that disrupted signaling programs involved cellular growth and stemness as well as migration and attachment." (PMID 29568366, 2018). "Overall, the in vitro and in vivo data regarding SELENOK deficiency and melanoma support further investigation into this protein as a potential therapeutic target." (PMID 29568366, 2018). "Herein, we provide evidence that SELENOK is indeed required for effective Ca2+ flux in human melanoma cells and SELENOK deficiency changes their growth and stemness properties, leading to poor proliferation and migration in vitro and in vivo." (PMID 29568366, 2018). "IP3Rs, though better known for roles in oncogenesis and stem cell differentiation, have also been implicated in CSC maintenance; loss of Selenoprotein K (SELENOK) impairs IP3R function in melanoma, reducing intracellular calcium and stemness gene expression such as PROM1." (PMID 40806720, 2025). "SELENOK deficiency inhibits the migration of human melanoma cells by reducing the Ca2+ flux." (PMID 35883755, 2022). "Interestingly, only one intact SELENOK allele was required for in vitro melanoma cell functions and in vivo tumor growth." (PMID 29568366, 2018). "According to research, the expression of SELENOK is required for the development of melanoma because SELENOK is necessary for the flux of Ca2+ ions into the cancerous cells." (PMID 37958974, 2023). "This suggests a threshold of SELENOK exists that is needed for efficient Ca2+ flux in melanoma cells, similar to what has been observed for immune cells." (PMID 29568366, 2018). "Overall, these data suggest that SELENOK expression is required for progression of primary melanoma tumors as well as metastasis to the draining lymph nodes." (PMID 29568366, 2018). "Our gene array data suggest that growing melanoma cells require SELENOK for proliferation and stemness transcriptional programs to modify their phenotype, we cannot categorical state that this is due solely on SOCE." (PMID 29568366, 2018). "Furthermore, in the domain of oncology research, existing studies have documented anti‐cancer properties of selenoprotein K in in vivo melanoma models and human melanoma cell lines." (PMID 41323827, 2025). "The SELENOK-deficient mice, which were born from the same litter, displayed reduced primary tumor growth, suggesting that Ca2+ release through IP3R is required for melanoma stemness and tumor development." (PMID 36142596, 2022). "The results were similar for males and females, suggesting no dimorphic effects of SELENOK deficiency on melanoma in this model." (PMID 29568366, 2018). "Thus, our results support a role for SELENOK in transcriptional programs supporting melanoma growth and stemness, but we cannot conclude that transcriptional changes are directly due to the effects of SELENOK on Ca2+ flux that causes the changes in gene expression levels." (PMID 29568366, 2018). "Ca2+ release through IP3R was shown to play an important role in melanoma CSCs, when the reduction of IP3R maturation after selenoprotein k (SELENOK) knockdown reduced Ca2+ release and led to a decrease in CD133+ populations." (PMID 36142596, 2022). "However, genetic manipulation of the SELENOK gene in vitro and in vivo leading to substantially lower levels of full-length protein clearly decreased SOCE in melanoma cells." (PMID 29568366, 2018). "To date, a role for SELENOK in cancer progression has not been described and the data presented herein suggest that this selenoprotein acts to promote melanoma tumor progression and metastasis." (PMID 29568366, 2018).
melanoma (continued). "This is consistent with our data in human tissues and NCI-60 melanoma cell lines showing that SELENOK protein levels are not increased in melanoma compared to normal cells or tissues." (PMID 29568366, 2018). "This suggests a high level of SELENOK protein is not necessarily required for malignant melanoma to progress." (PMID 29568366, 2018).
prostate carcinoma (4 papers, 2012 to 2021). A carcinoma that arises from epithelial cells of the prostate gland. "Polymorphisms in the genes for two members of the thioredoxin reductase family of selenoproteins (TXNRD1 and TXNRD2) and Selenoprotein K (SELENOK) associated with prostate cancer risk only when selenium status was also considered." (PMID 32806741, 2020). "SELENOK was also found to be over-expressed in gastric, glial, thyroid, testis, and cervix cancers, and its polymorphisms, in combination with selenium status, were related to prostate cancer progression." (PMID 32933107, 2020). "The findings contribute to explaining the biological effects of selenium intake and genetic factors in prostate cancer development and highlight potential roles of thioredoxin reductases and selenoprotein K in tumour progression." (PMID 23133653, 2012). "In prostate carcinoma cells, SeNP did not significantly affect the expression of the seven studied selenoproteins; a twofold increase in the expression of SELENOT, SELENOK, SELENON, and DIO2 can be noted." (PMID 34360564, 2021).
glioma (3 papers, 2020 to 2024). A benign or malignant brain and spinal cord tumor that arises from glial cells (astrocytes, oligodendrocytes, ependymal cells). "Furthermore, SELENOK inhibition by miR-181 and miR-544a was able to suppress the proliferation of glioma and hepatocellular carcinoma cells, respectively." (PMID 32933107, 2020).
atherosclerosis (2 papers, 2021 to 2023). A disease characterized by the build-up of fatty material and calcium deposition in the arterial wall resulting in partial or complete occlusion of the arterial lumen. "SELENOK expression was detected in aortic plaques, particularly in macrophages, and SELENOK KO animals exhibited reduced atherosclerosis as indicated by lesion formation, which may contribute to foam cell formation and atherogenesis." (PMID 34639053, 2021).
lung adenocarcinoma (2 papers, 2022 to 2023). A carcinoma that arises from the lung and is characterized by the presence of malignant glandular epithelial cells. "Amid the spectrum of genes spotlighted in our earlier prognostic signature, SELENOK emerged as a particularly intriguing candidate, warranting a deeper dive into its functional implications in lung adenocarcinoma (LUAD)." (PMID 37945620, 2023).
selenium deficiency (2 papers, 2020 to 2021). A nutritional deficiency disease resulting from inadequate selenium levels in the body, which can lead to impaired function of selenoproteins essential for antioxidant defense and thyroid hormone metabolism. "Selenium deficiency leads to reduction in the expression of selenoprotein K (SelK), which is expressed in the endoplasmic reticulum membrane of many immune cells including T cells." (PMID 33926483, 2021).
viral infection (2 papers, 2023). "Here, we identified that the endoplasmic reticulum (ER)-located transmembrane selenoprotein K (SELENOK) was induced during virus infection and facilitated innate immune responses against herpes simplex virus-1 (HSV-1)." (PMID 37023217, 2023). "SELENOK is upregulated during viral infection and enhances STING oligomerization to facilitate the activation of the cGAS-STING pathway and suppress viral replication." (PMID 37023217, 2023).
gastric cancer (1 paper, 2022). A primary or metastatic malignant neoplasm involving the stomach. "Still, overexpression of SELENOK inhibits the migration of human gastric cancer cells by increasing Ca2+ levels." (PMID 35883755, 2022).
liver cancer (1 paper, 2020). An epithelial or non-epithelial malignant neoplasm that arises from the liver. "Recently, we showed that SELENOK was over-expressed in two liver cancer cell lines, HepG2 and Huh7." (PMID 32933107, 2020).
metastatic melanoma (1 paper, 2018). A melanoma that has spread from its primary site to another anatomic site. "In vivo investigations were conducted using the Grm1-Tg transgenic mouse strain that develops spontaneous metastatic melanoma, which was crossed with SELENOK−/− mice to generate the following littermates: Grm1-Tg/SELENOK−/−, Grm1-Tg/SELENOK−/+, Grm1-Tg/SELENOK+/+." (PMID 29568366, 2018).
steatosis (1 paper, 2021). Increased lipid within the cytoplasm of cells. "Amongst the 13 genes, eight (DIO1, GPX2, SEPHS2, SELENOK, SELENOS, SELENOT, SELENOF, and SELENOW) had higher, and five (DIO3, GPX1, SELENON, SELENOO, and TXNRD3) had lower expression in steatosis." (PMID 34869521, 2021). "Of these genes, 11 coded for selenoproteins of which four genes had lower expression (SELENON, SELENOO, GPX1, and TXNRD3) and seven genes had higher expression (SELENOK, SELENOS, SELENOW, GPX2, GXP3, DIO1, and SEPHS2) in steatosis." (PMID 34869521, 2021).
tumor (13 papers, 2012 to 2026). "SELENOK-deficiency in Grm1-Tg/SELENOK−/− male and female mice inhibited primary tumor growth on tails and ears and reduced metastasis to draining lymph nodes down to levels equivalent to non-tumor control mice." (PMID 29568366, 2018). "It reduces the migration of choriocarcinoma cells by ERK, p38 MAPK and Akt pathways, suggesting that SELENOK has different effects on the migration of different tumours." (PMID 35883755, 2022). "SELENOK has essential functions in tumour cell invasion and migration, and the migration and phagocytosis of immune cells." (PMID 35883755, 2022). "By contrast, CPS1, a key enzyme in the urea cycle, and SELENOK, a regulator of ER-associated protein degradation and redox homeostasis, were largely absent or only weakly expressed in tumor sections." (PMID 41584048, 2026). "Interestingly, an uptick in SELENOK expression correlated with a more favorable prognosis, hinting at its potential tumor-suppressive role in LUAD." (PMID 37945620, 2023). "However, the mice in our experiments were followed up to 8 months of age and the Grm1/SELENOK–/– mice continued to exhibit lower levels of tumor formation compared to Grm1/SELENOK+/+ and Grm1/SELENOK+/– littermates for both sexes." (PMID 29568366, 2018). "In addition, SELENOK may act as suppressor of tumor in human choriocarcinoma cells by negatively regulating expression of β-human chorionic gonadotropin (β-hCG) via p38 MAPK, Akt and ERK signaling pathways." (PMID 29758013, 2018). "Only positive correlations of gene expression with the Se level were observed for the SELENOF, SELENOK, and TXNRD1 genes, all in the tumor tissue (p = 0.001, 0.004, and 0.04, respectively), except for the normal tissue expression of SELENOK as well (p = 0.03)." (PMID 30469315, 2018). "Also consistent with primary tumor data, SELENOK deficiency in the Grm1-Tg mice led to a reduction of Trp2-positive cells in the lymph nodes at levels similar to mice lacking tumors (C57BL/6J and SELENOK–/– controls)." (PMID 29568366, 2018).
cancer (7 papers, 2016 to 2025). A tumor composed of atypical neoplastic, often pleomorphic cells that invade other tissues. "While, the precise anti‐cancer molecular mechanisms remain to be explored in greater depth, it is evident that selenoprotein K has potential applications." (PMID 41323827, 2025). "Another possible explanation for the lack of influence of SELENOM-KD on the proliferative properties of cancer cells is the increased expression of SELENOK and SELENOT, two other selenoproteins localized in the ER." (PMID 35741332, 2022). "An additional explanation for why SELENOT-KD did not lead to the death of A-172 cancer cells and did not cause either oxidative stress or ER stress can be the increased activity of SELENOK." (PMID 35741332, 2022). "Additional genes in this study, showing changes in gene expression for both the Irish and the Czech cancers were GPX2, GPX3, SELENOK, SEPHS2, SELENBP1, and SOD2." (PMID 30469315, 2018). "Thus, GPX1, SELENBP1, SELENON, SELENOK, and SOD2 were differently expressed only in the cancer tissues." (PMID 30469315, 2018). "Signaling pathway analyses revealed how these factors and other signaling nodes that impinge upon cancer related functions were affected by the lack of functional SELENOK." (PMID 29568366, 2018). "A number of studies have shown the importance of SELENOK in maintaining IP3R-dependent Ca2+ flux in immune cells, but the data presented herein demonstrate a new role in promoting Ca2+-dependent functions such as proliferation and migration in cancer cells both in vitro and in vivo." (PMID 29568366, 2018).
infection (2 papers, 2018 to 2022). The state of being infected such as from the introduction of a foreign agent such as serum, vaccine, antigenic substance or organism. "Downregulation of SelP in infection/acute phase reaction may represent a mechanism to generate Se for incorporation into other selenoproteins that are more directly involved in immunity e.g. GPx1, TrxR1 and Selenoprotein K." (PMID 30571741, 2018). "Recently, infection of selenium-deficient Vero E6 cells with SARS-CoV-2 revealed a downregulation of SELENOF, SELENOK, SELENOM, and SELENOS localized in the ER, indicating that infection could adversely affect ER." (PMID 35563199, 2022).
SELENOK also shares sentences with these, for which no sentence is quoted: hepatocellular carcinoma (3 papers); abscess (1); adenoma (1); Alzheimer disease (1); Borrelia burgdorferi infection (1); cervix cancers (1); cognitive deficits (1); colorectal tumor (1); fibrosarcoma (1); glioblastoma (1); heart failure (1); influenza infection (1); metabolic disorders (1).